EZH2 (enhancer of zeste 2 polycomb repressive complex 2 subunit)
Diseases named in the same sentence as EZH2 in open-access papers (continued):
Sharing a sentence is not in itself a finding about the gene and the disease.
tumor (continued). "The discrepancy in our results may also reflect that TCGA data were generated from bulk tumor samples which capture a wide array of tumor cells that could have heterogeneous EZH2 expression." (PMID 34140011, 2021). "EZH2 has the same characteristics as oncogenes; its overexpression in vitro is closely related to cell proliferation, colony formation, and benign cell invasion, and it induces xenograft tumor growth in vivo." (PMID 34367971, 2021). "GSEA analysis revealed that this 37-gene signature was significantly associated with the GSK-J4 treatment, suggesting that KDM6B inhibition consequently downregulates the functions of PRC2, leading to the induction of tumor-suppressive program repressed by EZH2." (PMID 34893606, 2021). "Zinc finger protein 750 (ZNF750) and enhancer of zeste homolog 2 (EZH2), which were identified as the tumor suppressor in NPC, could inhibit the growth and metastasis of NPC cells." (PMID 33879256, 2021). "Mechanistically, we showed that circTP63 could competitively bind to miR-217 and promoted level of EZH2 expression, which finally facilitated tumor progression." (PMID 34789260, 2021). "EZH2 is overexpressed in numerous tumor entities including renal tumor cells." (PMID 33679454, 2021). "Enhancer of zeste homolog 2 (EZH2) is a novel oncogene that can specifically trimethylate the histone H3 lysine 27 (H3K27me3) to transcriptionally inhibit the expression of downstream tumor-suppressing genes." (PMID 34930462, 2021). "EZH2 plays a key role in tumor formation via epigenetic gene silencing and chromatin remodeling." (PMID 34381816, 2021). "Thus, EZH2 appears to rely on multiple cell context-dependent mechanisms to facilitate neoplastic transformation and sustain tumor growth." (PMID 33803922, 2021). "RT-qPCR and Western blot were conducted to measure the EZH2 expression in three tumor cells." (PMID 34381492, 2021). "Not much evidence exists regarding EZH2 in ccRCC but high tumor and initial reports suggested EZH2 level was associated with less aggressive tumor phenotypes and favorable prognosis." (PMID 33922974, 2021). "Taken together, EZH2 inhibition may promote NK-induced cytotoxicity by affecting both the tumor and NK cells." (PMID 34737746, 2021). "Moreover, EZH2 disruption leads to Tregs impairment and strengthens the anti-tumor immunity, which indicates the prominent role of H3K27me3 in Tregs." (PMID 33868279, 2021). "Furthermore, the effects of synergy between chemotherapies and the enhancer of zeste homolog 2 (EZH2) inhibition on tumor-inhibition of SCLC was demonstrated in PDX models, even in those that were resistant to chemotherapy." (PMID 34957199, 2021). "Regulation of epigenetic mediators of acquired tumor immune escape (such as EZH2, DNMTs, HDACs, Bromodomain and ExtraTerminal (BET) family members, and Lysine-specific demethylases) may overcome the immunotherapy resistance in PCs." (PMID 34830196, 2021). "Ezh2 inhibition enhanced NK cell eradication of tumor cells in hepatocellular carcinoma." (PMID 34017344, 2021). "Accumulating evidence highlights the importance of EZH2 in promoting cancer cell immune escape in different types of malignancies and in shaping different tumor-infiltrating immune cells, overall supporting both immunosuppressive activities and antitumor immunity." (PMID 33922336, 2021). "We also observed that EZH2 levels in tumor (compared to normal) tend to be higher in TNBC cases." (PMID 33750924, 2021). "Akt-mediated phosphorylation of Ezh2 in T cells resulted in reduced formation of memory precursor T cells, suggesting Akt-mediated phosphorylation of Ezh2 as a target to potentially enhance anti-tumor T cell response." (PMID 33403469, 2021). "As RB has EZH2 overexpression and pharmacological inhibition of EZH2 in human RB cells shows a clear anticancer activity, preclinical studies on EZH2 inhibitors in RB tumor models will be required to further strengthen a possibility of clinical trials for these compounds in RB treatment." (PMID 32840881, 2021).
tumor (continued). "Only 21% of tumors (n = 36/172) showed a percentage of EZH2-positive tumor cells >3%." (PMID 34638497, 2021). "This suggests that EZH2 is not only a therapeutic target, but also a potential tumor biomarker." (PMID 34859108, 2021). "Among the different tumor types that depend on the abnormal growth of EZH2, a better study of tazemetostat administration based on biomarkers may be helpful for clinical drug usage." (PMID 34001246, 2021). "Additionally, EZH2 contributes to tumor invasion and metastasis through the modulation of angiogenesis and the epithelial-to-mesenchymal transition." (PMID 34140011, 2021). "Mechanistic study revealed that SNHG6 could recruit EZH2 and maintain high level of H3K27me3 to repress the transcription of tumor-suppressor genes, including KLF6." (PMID 33431838, 2021). "The pRb-E2F signaling pathway, for instance, induces EZH2 expression in several tumor entities." (PMID 34943970, 2021). "A heterogeneous response to EZH2 inhibition in PDOs was observed, which correlated with H3K27me3 expression in both tumor organoids and matched patient tumors, demonstrating organoids’ capacity to maintain the original tumor’s epigenetic signatures." (PMID 34957115, 2021). "In addition, we wanted to obtain more insight by examining those genes whose TSSs exhibited tumor-gained H3K4me3 signals and EZH2/SUZ12 TFBS." (PMID 33916417, 2021). "However, 120 mg/kg SHR2554 just induced moderate tumor suppressive activity in EZH2 wild-type models U2932 and PDX001, which was consistent with the previous results in vitro." (PMID 34503063, 2021). "miR-340 could significantly attenuate Hep-2 cell-derived tumor growth through the EZH2/p27 signaling pathway in vitro and in vivo." (PMID 34455918, 2021). "EZH2 expression was evaluated in tumor epithelium of all subjects included in the study." (PMID 34140011, 2021). "The GEPIA2 tool was also used to observe the EZH2 expression in different tumor stages." (PMID 34381492, 2021). "We found that “Cell cycle” and “Viral carcinogenesis” might be involved in the effect of EZH2 on tumor pathogenesis." (PMID 34381492, 2021). "Moreover, dysregulation of EZH2 levels in CLL results in intra-tumor heterogeneity contributing to drug resistance." (PMID 34200679, 2021). "However, further studies are warranted to clarify the role of EZH2 in the regulation of biological behavior of the tumor." (PMID 35186711, 2021). "Finally, another study had shown that anti-PD-1 treatment in association with inhibition of the methyltransferase EZH2 induced an increase of intratumoral activated CD8+ T cells and M1 tumor-associated macrophages (TAMs), reducing tumor growth." (PMID 34830179, 2021). "Indeed, EZH2 levels are higher in SCLC than any other tumor type in TCGA, and EZH2 inhibitors can restore SLFN11 expression to potentially improve response to PARP inhibitors." (PMID 33578789, 2021). "Thus, we believe that the effect of the drug on the tumor is specific to its documented ability to inhibit EZH2 mediated histone methylation." (PMID 34336705, 2021). "Therefore, initiation of a clinical strategy by specific EZH2 inhibitors must go through a complete understanding of the molecular aspects that characterize tumor initiation." (PMID 34372908, 2021). "Increased EZH2 function may favor immunosuppressive tumor microenvironments and immunotherapy resistance." (PMID 34830196, 2021). "We interrogated whether the regulation of CERK by EZH2 could be a general phenomenon in this tumor type." (PMID 34503116, 2021). "The results revealed that EZH2 was upregulated in various tumor types." (PMID 34381816, 2021). "We did not analyze the mechanisms underlying EZH2 overexpression in our tumor cohort, but there is evidence from the literature that NF-kB, MUC1-C, KRAS, MEK-ERK and PI3K-AKT signaling might cause significant EZH2 up regulation in human cancers." (PMID 32303902, 2021).
tumor (continued). "Consequently, activated ErbB proteins confer resistance to infigratinib by switching the growth dependence to the EZH2/ErbB pathway, allowing resistant nodules to grow and form the bulk of the tumour." (PMID 34156519, 2021). "For example, EZH2, a methyltransferase, is closely related to tumor metastasis and proliferation." (PMID 33996555, 2021). "They further observed robust EZH2 secretion in epithelioid cells with a high Ki67 index but not in low-grade lesions which suggested that EZH2-positive cells are associated with intratumoral heterogeneity as well as the malignant progression of the tumor." (PMID 34745848, 2021). "Remarkably, the activation and tumor-promoting traits of TAFs were rescued by inhibition of H3K27 trimethylation with the EZH2 histone methyltransferase inhibitor DZNep as well as the general methyltransferase inhibitor 3-DZA, further underscoring the role of altered histones in TAF activation." (PMID 34359678, 2021). "However, contradictory results have been found regarding the regulatory effect of tumor EZH2 on PD-L1 expression." (PMID 34737746, 2021). "As inhibition of EZH2 activity could upregulate the expression of tumor suppressor genes, EZH2 has recently become an interesting therapeutic target for cancer therapy." (PMID 34737746, 2021). "Based on this synergistic anti-tumor capacity, co-administration of EZH2 inhibitor and HDAC inhibitor could provide a potential therapeutic strategy for DLBCL patients." (PMID 34503063, 2021). "Hypermethylated promoter regions in ALK tumor cells showed strong enrichment of binding sites for proteins associated with chromatin remodeling in ESC, in particular PRC associated proteins including CBX7, EZH2, MTF2, PHF19, RING1B, RNF2, and SUZ12." (PMID 33310759, 2021). "The combination of HDAC inhibitor HBI8000 and EZH2 inhibitor SHR2554 exhibited dramatic anti-tumor activity in both mutant and wild-type DLBCL, which could provide a potential therapeutic modality for the treatment of DLBCL patients." (PMID 34503063, 2021). "These combined findings suggest a dual role of EZH2 as either tumour suppressor or oncogene." (PMID 33712646, 2021). "Some of these, such as EZH2 or G9A, are good molecular markers in bladder tumor tissue, which can help to discern the nature of a tumor subtype and the prognosis of patients and can also cooperate or regulate other epigenetic elements which are biomarkers in the clinic." (PMID 34072826, 2021). "We also examined whether the association between EZH2 expression and RTT varied by tumor immune features." (PMID 34140011, 2021). "More importantly, we showed that the combination of epigenetic treatments significantly downregulated the expression of DNA replication initiator protein ORC1 regardless of EZH2 mutation status of tumor cells." (PMID 34503063, 2021). "A combinatorial treatment sensitized resistant EZH2-overexpressing tumor cells to EZH2 inhibition." (PMID 33568205, 2021). "Also, a histone methyltransferase EZH2 was recently reported to show opposing (oncogenic and tumor‐suppressive) roles during the initiation and maintenance of the same AML." (PMID 34938963, 2021). "EZH2 can also affect tumor progression by regulating metabolism." (PMID 34737746, 2021). "NPC progression known to be associated with Epstein-Barr Virus-encoded latent membrane protein 1 (LMP1) also drives expression of EZH2 in activated Treg cells, which was antagonized by treatment with Dznep, leading to depletion of Treg cells and enhanced anti-tumor immunity." (PMID 34930302, 2021). "Moreover, in vivo studies revealed that these EZH2 inhibitors showed significant tumor growth inhibition in lymphoma and myeloma." (PMID 34440583, 2021).
tumor (continued). "Thus, mechanistically, elemene and gefitinib combination therapy inhibits EZH2 and PD-L1 levels and the cancer-stem phenotype, reverses the mesenchymal phenotype, and inhibits their ball-forming ability, thereby inhibiting tumor development in xenograft mice." (PMID 34641334, 2021). "Thus, HNF1B appears as a direct downstream target of EZH2, and its tumor suppressor role is mediated by repression of SLUG expression and EMT process." (PMID 34199763, 2021). "Previous studies have shown that EZH2 regulates a wide variety of miRNAs (including miR-181a) by increasing the levels of the epigenetic silencing marker H3K27me3, and EZH2 epigenetically silences tumor suppressor miRNAs through H3K27 trimethylation in EC cells." (PMID 34174908, 2021). "Restored expression of EZH2 could reactivate AKT/MTOR pathway in the tumours formed by inhibiting PTEN." (PMID 32814835, 2020). "Many studies have found that EZH2 is highly expressed in tumor tissue compared with normal tissue, and its expression level is positively related to the gender and bad prognosis of tumor, which can be acted as an important index for predicting the prognosis of human tumors." (PMID 33072570, 2020). "For different tumor status, EZH2 and ODF2 expressed differently." (PMID 32699528, 2020). "Considering that EZH2 is highly expressed in multiple malignant tumors and its expression is positively correlated with metastasis, EZH2 may be a new target of tumor therapy." (PMID 33072570, 2020). "Importantly, overexpression of EZH2 or H3K27me3 protein levels were found to be independent predictors of overall and progression-free survival after multivariate analysis for tumor size, histologic grade and clinical stage." (PMID 33050946, 2020). "In consistency with our findings, overexpressed EZH2 has been previously correlated with shorter survival among OC patients, and EZH2 depletion could not only reduce tumor cell proliferation but also suppress the drug resistance in OC." (PMID 33292225, 2020). "However, EZH2 is significantly overexpressed in tumor PC from the MGUS stage, and its expression, which correlates with the cell proliferation index, increases during the progression to SMM, reaching a maximum at the PCL stage." (PMID 33126754, 2020). "This epigenetic switch may bring about an oncogenic addiction to the H3K27ac modification in EZH2 insufficient tumor cells." (PMID 33374737, 2020). "Meanwhile, we also found that GO could downregulate the expression levels of H3K27me3 and EZH2 in U87 tumor cell, with a weaker degree." (PMID 32410622, 2020). "Knockdown of EZH2 suppressed TNBC MDA-MB-231 tumor growth and metastasis in xenograft models." (PMID 32206036, 2020). "Being one of the key factors involved in epigenetic regulation, EZH2 may regulate the metabolic activities of tumor cells, thereby affecting cancer progression." (PMID 32448308, 2020). "EZH2 mediates H3K27me3 silencing of tumor suppressor genes, enabling CSC expansion." (PMID 32532153, 2020). "The authors performed an RNA transcriptome comparison between SNHG1 knockout and control cells and found differential expression of hundreds of transcripts, including the established tumor suppressor and EZH2 target CDKN1A, which showed significant upregulation upon SNHG1 knockout." (PMID 32331331, 2020). "Nevertheless, the restored expression of EZH2 could reactivate AKT/mTOR pathway in the tumours formed by E2F7-silencing cells." (PMID 32814835, 2020). "The subcutaneous tumor formation rate decreased from 100 to 0% in the EZH2 knockout group." (PMID 33163485, 2020). "This also suggests to some extent that EZH2 not only promotes tumor progression but may play a beneficial role in certain tumors or certain tumor subtypes." (PMID 33299862, 2020). "EZH2 and H3K27me3 expression has been linked to a downregulation of immune response genes by negatively regulating interferon response genes, TH-1 type chemokines and MHC expression in tumor cells." (PMID 32041674, 2020).
tumor (continued). "Furthermore, YY1 affects the activity of enhancer of zeste homolog 2 (EZH2) in catalyzing histone H3 lysine 27 trimethylation (H3K27me3) and suppressing tumor suppressor miR-9 activity through DNA methylation." (PMID 32226547, 2020). "EZH2 expression is particularly high in SP cells and in some tumor PC." (PMID 33126754, 2020). "Numerous studies have previously shown that upregulation of EZH2 is correlated with cell proliferation and poor tumor prognosis; thus, in UM, a high level of EZH2 expression has been demonstrated, suggesting that it is an oncogenic protein in this type of neoplasm." (PMID 33053887, 2020). "EZH2 was reported to function as an upstream regulator of miR-139-3p and could mediate the tumor-suppressive role of miR-139-3p." (PMID 33292225, 2020). "Looking back the research history regarding EZH2, although it has been found closely correlated with majority of tumor genesis, metastasis, and prognosis in decades, the effectiveness in previous clinical trials targeting EZH2 was not satisfactory, especially in solid tumor." (PMID 32448308, 2020). "Besides, EZH2 expression was also positively correlated with KDM2B, which was significantly associated with tumor histological type, stage, and lymph node metastasis." (PMID 33163485, 2020). "We therefore selected EZH2 target genes with tumour‐suppressive functions (KLF2, RND1 or PTEN) that could be involved in the link between SNHG7 and OC progression." (PMID 32420685, 2020). "In contrast, Ezh2 acts as a tumor suppressor during the induction phase of AML." (PMID 33374737, 2020). "H3K27me3 is required for EZH2-mediated repression of various genes essential for tumorigenesis and tumor development, while the expression of H3K27me3 and EZH2 could serve as biomarkers in the prediction of ESCC patients’ survival and ESCC metastasis." (PMID 33330444, 2020). "EZH2 was higher in tumor tissues than in adjacent nontumor tissues and was associated with poor prognosis in tumor patients." (PMID 32206036, 2020). "Dual EZH1/EZH2 inhibition may have greater anti-tumor efficacy because EZH1 can compensate when EZH2 is inhibited." (PMID 32723346, 2020). "As a result, EZH2 promotes glucose metabolism and facilitates tumor cell survival." (PMID 32448308, 2020). "Interestingly, the gene expression profile (GEP) of EZH2-overexpressing tumor PC resembles that of HMCLs." (PMID 33126754, 2020). "Compared with the NC group, the expression levels of p-PI3K, p-AKT, p-mTOR, and p-p70S6K in the tumor tissue in the si-SNHG1 group were significantly reduced; the expression levels of p-PI3K, p-AKT, p-mTOR, and p-p70S6K in the tumor tissue in the si-SNHG1+EZH2 group were significantly increased." (PMID 33194612, 2020). "In some cases, mutations in genes encoding histone H3K27 reduce levels of H3K27me3, even in the absence of loss-of-function EZH2 mutations, leading to tumor development." (PMID 33374737, 2020). "Moreover, in agreement with these results, previous studies reported that the EZH2 loss-of-function mutations and SRSF2Mut occur in the same spectrum of malignant myeloid disorders, where EZH2 seems to behave as a tumor suppressor." (PMID 33321981, 2020). "Furthermore, the binding of NEAT1 and ALKBH5 can negatively affect the expression of EZH2, thereby promoting tumor cell invasion and metastasis." (PMID 33291485, 2020). "This study detected that patients with advanced tumor stage, high EZH2, and high EZH2 with negative ER status had a high risk for ALN metastases in the univariate analysis (p=0.014; 0.003; 0.013)." (PMID 33235571, 2020). "Based on this in vivo data, we hypothesized that EZH2 exerted its tumor-promoting function in HCC via down regulating miR-200c expression." (PMID 33168810, 2020). "High EZH2 expression was present in 62% of all NSCLCs and its expression was positively associated with non-adenocarcinoma histology, higher tumor stage (T2-T4), histologic grade and proliferation index." (PMID 33050946, 2020).